MIR548F1 (microRNA 548f-1)
Synonyms: hsa-mir-548f-1; MIR548F-1; MIRN548F1
Gene: MicroRNA gene on chromosome 10 (54,607,874 to 54,607,957, reverse strand). Ensembl gene ENSG00000221594.
Homologues: Orthologues: chimpanzee MIR548F1 (99% identical). Paralogues in human: MIR548P (82% identical), MIR548AZ (81% identical), MIR548F3 (81% identical), MIR548H3 (79% identical), MIR548AA1 (76% identical), MIR548K (75% identical), MIR548AN (74% identical), MIR548X (73% identical), MIR548X2 (73% identical), MIR548Z (73% identical), MIR548AY (71% identical), MIR548AH (70% identical), and 13 more.